Y_RNA (Y RNA )
Gene: Miscellaneous RNA gene on chromosome 22 (41,747,312 to 41,747,413, forward strand). Ensembl gene ENSG00000206813.
Homologues: Orthologues: chimpanzee Y_RNA (100% identical), macaque Y_RNA (97% identical). Paralogues in human: RNY3P14 (90% identical), Y_RNA (90% identical), RNY3 (89% identical), Y_RNA (89% identical), RNY3P1 (88% identical), Y_RNA (88% identical), RNY3P5 (87% identical), Y_RNA (87% identical), RNY3P10 (86% identical), Y_RNA (86% identical), Y_RNA (85% identical), Y_RNA (84% identical), and 95 more.